HHLA2 (HHLA2 member of B7 family)
Diseases named in the same sentence as HHLA2 in open-access papers (continued):
Sharing a sentence is not in itself a finding about the gene and the disease.
cancer (continued). "In order to reveal the expression pattern of HHLA2 in various cancers, we downloaded RNAseq data of pan‐cancer from the UCSC Xena database." (PMID 34152094, 2021). "Our results demonstrated that high HHLA2 expression predicted poor OS in Chinese patients with cancers." (PMID 34397730, 2021). "HHLA2 is expressed in about 20 to 70% of large number of human cancers including lung, thyroid, breast, pancreas, melanoma, bladder, colon just to name a few." (PMID 34320928, 2021). "HHLA2 can inhibit the function of CD4 and CD8 T cells, and blocking HHLA2 can enhance the proliferation and activation of T cells, which is helpful for cancer immunotherapy." (PMID 34660693, 2021). "Subgroup analysis by cancer type showed that HHLA2 overexpression was correlated with poor OS in patients with ccRCC, GC, ICC, LC, and other cancer types, but not in patients with EOC." (PMID 34397730, 2021). "Novel immunotherapeutic approaches targeting HHLA2 are under active development and have demonstrated hopeful results in many studies on other cancers." (PMID 34181347, 2021). "The mechanism should be further studied to reveal the influence of HHLA2 expression on the types of cancer." (PMID 34397730, 2021). "In our study, patients with KIRC showed higher levels of HHLA2 in cancer tissues than in normal kidney tissue, based on TCGA data." (PMID 32509772, 2020). "Here, we employed TCGA database and TMAs to investigate the expression pattern of HHLA2 in a several cancer types." (PMID 32509772, 2020). "In multivariable analysis together with clinicopathologic characteristics, higher HHLA2 expression was an independent predictor of cancer-specific survival." (PMID 32071413, 2020). "Using The Cancer Genome Atlas (TCGA) database, we investigated the expression pattern of HHLA2 across 22 types of cancer." (PMID 32509772, 2020). "Till now, the relationship between HHLA2 expression and immune cell infiltration in various cancers is still debatable." (PMID 31959726, 2020). "In 77% of tumours we observed HHLA2 expression in cancer cells; expression was graded as low in 49% and as high in 28% of tumours." (PMID 32071413, 2020). "Previous studies reported discrepant results among different cancer types on the correlations between immune cell infiltration and HHLA2 expression." (PMID 30885276, 2019). "HHLA2 was previously observed with expression rates ranging from zero to 70% in a variety of cancer types." (PMID 30885276, 2019). "The positive staining of HHLA2 was predominantly found in the cytoplasm and on the membrane of the cancer cells." (PMID 31015801, 2019). "Herein, we aimed to study the clinical implications of HHLA2 expression in human ccRCC and its potential regulatory role in the biological functions of the cancer cells." (PMID 31015801, 2019). "The significant prognostic significance of HHLA2 was determined in 10/20 tumors in this pan-cancer analysis." (PMID 31379814, 2019). "Pan-cancer survival analysis indicates that HHLA2 was an independent prognostic factor in 9/20 of human cancers." (PMID 31379814, 2019). "Then, the pan-cancer expression profiling of HHLA2 was visualized according to TCGA data by TIMER platform." (PMID 31379814, 2019). "The exploration of HHLA2 within endocrine-related cancer research remains limited." (PMID 40255615, 2025). "Indeed, early studies reported the immunsuppressive effects of several possible immune checkpoints, including CD276, Siglec-15, B7x, HHLA2, and PD-L2 in patients with PD-L1lo/– cancer." (PMID 40985894, 2025). "In addition, in OC, the contrasting effects of HHLA2 expression in tumor versus stromal compartments illustrate the importance of the TME in influencing cancer outcomes." (PMID 40255615, 2025). "In the prospect of potential immunotherapies targeting HHLA2, it is important to establish its co-expression patterns with other immune checkpoint genes in various types of cancer, as they could affect the effects of such treatment." (PMID 38786018, 2024).
cancer (continued). "HHLA2 expression was also demonstrated to be an independent predictor of cancer-specific survival." (PMID 38786018, 2024). "In the prospect of the potential immunotherapies targeting HHLA2, it is essential to establish its co-expression patterns with other immune checkpoint genes in various types of cancer, as they could influence the effects of such treatment." (PMID 38731979, 2024). "Silencing HHLA2 could be helpful in cancer treatment because it has been shown to improve clinicopathological conditions such as survival and decrease tumor size, cancer cell invasion, migration, and proliferation." (PMID 38731979, 2024). "Moreover, HHLA2 levels were elevated in the urine of patients with cancer compared with healthy controls." (PMID 38786018, 2024). "There are various cancers in which HHLA2 is expressed more frequently than PD-L1." (PMID 38786018, 2024). "Moreover, HHLA2 mRNA and protein levels were increased in the cancer tissue compared with the paired adjacent normal tissue." (PMID 38786018, 2024). "HHLA2 expression in cancer tissues showed a weak linear relationship with HHLA2 mRNA blood levels." (PMID 38786018, 2024). "Importantly, HHLA2 expression in cancer cells correlated with the expression of another B7 family molecule—B7-H3 (p < 0.0001)—and the association between HHLA2 and B7-H4 expression was negative." (PMID 38786018, 2024). "This relation reveals the critical role of HHLA2 in cancer immunity." (PMID 36982953, 2023). "HHLA2 is a novel immune checkpoint molecule belonging to the B7 family of ligands and is widely expressed in cancer samples and participates in the growth and development of various cancers." (PMID 36982953, 2023). "HHLA2 has a restricted expression in normal human tissues but a broad one in human cancers." (PMID 36982953, 2023). "High expression of HHLA2 has been shown to be negatively correlated with overall survival in patients with hepatocellular carcinoma and positively correlated with lymphatic metastasis of certain cancers." (PMID 37865763, 2023). "TMIGD1 and HHLA2 were previously reported to be potential therapeutic targets in cancers." (PMID 35506368, 2022). "In addition to HLA, KIR3DL3 was more recently discovered as a novel interaction partner for HHLA2 (a immune checkpoint member of the B7 family), which has both immune inhibitory and activating abilities and is expressed in many human cancers." (PMID 36178190, 2022). "In vitro, HHLA2 overexpression boosted cancer cell progression and metastatic potential." (PMID 35371079, 2022). "However, HHLA2 is highly expressed in various malignant tumors, which makes HHLA2 a potential therapeutic target for human tumors." (PMID 35754803, 2022). "Second, the cut-off values of high HHLA2 expression were inconsistent, which may affect the effectiveness of HHLA2 as a predictor of cancer prognosis." (PMID 34397730, 2021). "Two recent studies indicated that KIR3DL3 might down-regulate NK cell functions through binding to HHLA2 (also called B7-H7), a B7 family molecule expressed on antigen-presenting cells and highly expressed in many human cancers." (PMID 34503073, 2021). "Expression of HHLA2 at high levels also is detected in various types of cancer." (PMID 34639059, 2021). "Additionally, the Cancer Cell Line Encyclopedia database was used to analyse the correlation between HHLA2 expression and PD-L1 or B7x expression." (PMID 33962626, 2021). "Fourth, HHLA2 may act differently in patients with PDAC than in other cancer types, and PDAC patients were also included in the study." (PMID 34397730, 2021). "HHLA2 may serve as a potential prognostic biomarker for solid tumors in Chinese population, by predict the prognosis of cancer patients based on their tumor types." (PMID 34397730, 2021). "Taken together, we provide evidence that HHLA2 may participate in cancer immune evacuation and cancer genesis." (PMID 33962626, 2021).
cancer (continued). "Interestingly, the HHLA2 pathway is considered an appropriate target for cancer immunotherapy using ICIs and treatment with antibody-drug conjugates (ADCs)." (PMID 34639059, 2021). "HHLA2 is a multifunctional protein that is abnormally expressed in various cancers." (PMID 34152094, 2021). "From the previous work on virus and cancer data we observed the expression pattern for HHLA2 and MAGEB5 across all samples suggesting that they could co-express and co-function together." (PMID 34320928, 2021). "Meta-analysis of HHLA2 and clinicopathological features in cancer patients." (PMID 34397730, 2021). "This highlights that the prognostic value and clinical significance of HHLA2 expression in various cancers may be complex and affected by many factors." (PMID 32509772, 2020). "HHLA2 is a recently discovered member of the B7-family of immune checkpoint molecules with limited expression in normal tissues but overexpression in several types of cancer." (PMID 32071413, 2020). "In multivariable analysis, HHLA2 expression, tumour differentiation grade (poor as compared to well-differentiated), margin status and lymph node status were independent predictors of cancer-specific survival." (PMID 32071413, 2020). "The different datasets or cohorts used in these studies may also lead to the contradictory prognostic value of HHLA2 in cancers." (PMID 32509772, 2020). "HHLA2 was widely expressed in cancers at both the mRNA and protein levels." (PMID 32509772, 2020). "In order to further investigate the potential contribution of HHLA2 to cellular function and signal pathways of human ccRCC cells in cancer progression, we performed the Agilent lncRNA microarray analysis to identify the differentially expressed genes profiles between LV-HHLA2-sh1 and LV-NC groups." (PMID 31015801, 2019). "Our results showed that the EMT marker E-cadherin expression was significantly increased, and N-cadherin as well as Vimentin was significantly decreased after knockdown of HHLA2 expression, suggesting that HHLA2 was involved in the cancer progression of human ccRCC by promoting EMT." (PMID 31015801, 2019). "Next, we investigated whether the expression of HHLA2 is elevated in human cancer compared with normal tissue." (PMID 31379814, 2019). "These literature altogether indicated that HHLA2 was potentially involved in cancer progression through immune inhibition and could be a promising target next to PD-L1 for cancer immunotherapy." (PMID 30885276, 2019). "HHLA2 is a member of the B7 family and has been shown to be broadly overexpressed in human cancers." (PMID 31089395, 2019). "Recent studies have investigated the expression of HHLA2 in various cancer cells." (PMID 29774123, 2018). "Therefore, HHLA2 is a potential target for cancer immunotherapy." (PMID 39132150, 2024). "Targeting HHLA2 could be beneficial in cancer treatment because its silencing has been shown to improve clinicopathological conditions such as survival, decreased tumor size, cancer cell invasion, migration, and proliferation." (PMID 38786018, 2024). "The prognosis prediction value of HHLA2 for various cancers remains unclear." (PMID 38731979, 2024). "Therefore, the specific modulation of one HHLA2 site may be a prospective approach to cancer immunotherapy." (PMID 36982953, 2023). "Bioinformatics experiments revealed that HHLA2 may accelerate the cell cycle of cancer cells." (PMID 35371079, 2022). "However, the prognostic impact of HHLA2 in human cancers remains controversial." (PMID 34397730, 2021). "Further analysis of the expression and genomic interaction of identified epitope peptides between HHLA2 and MAGEB5 in relation to specific immune variants provides a good basis of therapeutic approaches to inhibit this reaction and prevent viral effects related to chronic diseases and cancers." (PMID 34320928, 2021).
cancer (continued). "Thus, cancer type was the main source of heterogeneity and HHLA2 expression may play a different role in different types of cancer, especially in patients with PDAC." (PMID 34397730, 2021). "Therefore, targeting HHLA2 may inhibit cancer dissemination through immune-independent pathways and the underlying molecular basis requires further investigation." (PMID 30885276, 2019). "Recent studies have revealed a contrast in HHLA2 expression between tumor cells and the TME in various cancers." (PMID 40255615, 2025). "Notably, mRNA levels did not associate with HHLA2 protein levels, indicating that HHLA2 may be expressed mainly in the tumor microenvironment and not predominantly in cancer cells." (PMID 38786018, 2024). "Therefore, HHLA2/receptors may be a potential new block pathway improving cancer immunotherapy." (PMID 38786018, 2024). "The patients with low HHLA2 expression exhibited longer OS (p = 0.01), while high expression of B7-H3, B7-H4, and HHLA2 corresponded to worse OS and CRS (cancer-related survival)." (PMID 38786018, 2024). "This study revealed that increased t-HHLA2 expression is related to lower NLR, and increased s-FAP expression is related to higher CRP levels, which is also a cancer biomarker." (PMID 36598731, 2023). "Our findings showed that MLKL was positively correlated with the expression of immune checkpoints such as PD1, PD-L1, PD-L2, and CTLA4 in most cancer types, except for ICOSLG, CD200, CEACAM1, HHLA2, and VTCN1 in BUC." (PMID 37000317, 2023). "Based on an analysis of 30 human cancers, ATP7B expression was related to immunostimulatory activity, including ESCA(HHLA2:rho = 0.677, p < 2.2e-16; TNFRSF18:rho = -0.614, p < 2.2e-16)." (PMID 38037104, 2023). "In CPTAC-ccRCC, the protein expression of genes AR, GNB3, HHLA2, LIMCH1, and SAA1 had statistical significance in some comparisons of normal samples and cancer stage (Figure A9a–e)." (PMID 35565241, 2022). "The expression levels of HHLA2, PD-L1, CD8, and CD4 in cancer tissues from cases (206 in the training cohort and 197 in the validation cohort) with surgically resectable primary ccRCC were evaluated by immunohistochemistry." (PMID 31959726, 2020). "Targeting the HHLA2/KIR3DL3/TMIGD2 pathway, which we intend to explore in the future work, may be beneficial for cancer treatment and improve clinicopathological conditions such as survival." (PMID 38731979, 2024). "As a newly discovered member of the B7 family, HHLA2 is absent in most normal tissues, but is over-expressed in some malignant tumors." (PMID 38762741, 2024). "HHLA2 is upregulated in HCC, and positively correlated with more advanced stage, poor differentiation state, microvascular invasion and worse prognosis of such cancer type." (PMID 38144305, 2023). "The function of HHLA2 as a suppressive and stimulatory immune checkpoint in TME may be related to the predominance of different receptor interactions in different cancer types." (PMID 36499340, 2022). "Overall, the results hinted us that HHLA2 may be a potential prognostic predictor in SKCM and other cancers." (PMID 36003385, 2022). "HHLA2 is a newly discovered B7 family molecule, the interactions between B7 molecules and CD28-family receptors are crucial in cancer immunity, the aberrant expression of co-inhibitory B7 molecules has been attributed to reduced anti-tumor immunity and cancer immune evasion." (PMID 36003385, 2022). "Moreover, we also explored the contribution of HHLA2 to pathogenesis and progression of human ccRCC, and further confirmed that HHLA2 was involved in the promotion of EMT during cancer progression." (PMID 31015801, 2019). "In addition, five PRIs (HHLA2, IL2RA, TNFRSF18, TNFSF14, and CTLA4) included in the signature were regarded as potential PLAUR-related biomarkers in KIRC, which were studied in other cancers including KIRC based on the current literature." (PMID 36052236, 2022).
cancer (continued). "Some researches have demonstrated that HHLA2 promotes T-lymphocyte proliferation and cytokine release when interacting with the TMIGD2 receptor, which suggests that HHLA2 and TMIGD2 function through a co-stimulatory pathway to stimulate T cells to eliminate cancer cells." (PMID 33962626, 2021). "HHLA2 staining intensity of cancer cells was graded as absent, low, intermediate or strong." (PMID 32071413, 2020). "Therefore, our present results unveil that the abnormal expression of HHLA2 might promote the cancer progression in certain biological process but not via the regulation of CD8+ T cell infiltration or intratumoral angiogenesis." (PMID 31015801, 2019). "The expression of Melanoma associated antigens (MAGE) have also been shown to be highly expressed in TNBC but co-expression of HHLA2 and MAGE related genes especially MAGEB5 have not been demonstrated in any cancer type." (PMID 34320928, 2021). "Moreover, the HHLA2 pathway is independent of PD1/PD-L1 and, therefore, seems to be a promising target for immunotherapies in cancers resistant to any PD-L1 therapies." (PMID 38786018, 2024). "At this time there are no inhibitors of HHLA2 available for clinical use, but preventing immune tolerance, by targeting PD-L1 or CTLA-4, in the tumor microenvironment has proven effective in a variety of other cancers." (PMID 27531281, 2016).